EIF6 (eukaryotic translation initiation factor 6)
Diseases named in the same sentence as EIF6 in open-access papers (continued):
Sharing a sentence is not in itself a finding about the gene and the disease.
tumor (continued). "eIF6 has been linked to a variety of processes, including tumor biology and regulation of metabolism, and importantly, noncanonical roles of eIF6 in wound healing have been reported." (PMID 35024764, 2022). "Therefore, it is reasonable to conclude that eIF6 is a critical regulator of tumor growth." (PMID 35707354, 2022). "Notably, in tumor tissues, eIF6 was mostly diffused in the cytoplasm." (PMID 34922580, 2021). "In the present study, eIF6 was found to promote LUAD cell proliferation and colony formation in vitro, whilst increasing in-situ tumor growth." (PMID 36435920, 2023). "The combined expression score for all tumours (EOC and BL) in eEF1A1, eIF2α, eIF5B and eIF6 nuclear expression was equal (CS = 0)." (PMID 35718769, 2022). "Regarding biological functions, we demonstrated that eIF6 expression influenced preoperative FDG uptake and involved in immune cell infiltration in ESCA, which provides novel insights to the tumor biology." (PMID 35794622, 2022). "Amplification of eIF6 promoted the growth, migration and invasion capabilities of OSCC cell lines in vitro and tumor growth in vivo." (PMID 34922580, 2021). "We performed a microarray analysis of tumor tissue samples from OSCC patients and noticed that eIF6 was highly expressed in cancer tissues compared to normal tissue." (PMID 34922580, 2021). "Here we show that reducing eIF6 levels or treating cells with the PKCβ blocker Enzastaurin, restricts MPM cell line growth, in vitro, and tumor development and angiogenesis, in vivo, in an immunocompromised murine model." (PMID 26462016, 2015). "CAFs-Exo was found to be involved in tumor immune regulation through hsa-miR-139-5p, ACTR2 and EIF6, while PIGR, CD81, UACA and PTTG1IP may be potentially effective targets for the treatment of OSCC in the future." (PMID 37365497, 2023). "When eIF6 takes effect, it remarkably upregulates the functional network related to cell movement, like the CDC22, which can significantly increase the migration and invasion of tumor cells." (PMID 34922580, 2021). "In CRC, OV and MPM, eIF6 is overexpressed in tumor tissue compared to non-neoplastic tissue, highlighting that eIF6 as a potential new biomarker had a pivotal contribution to pathologic process." (PMID 34016142, 2021). "The results showed a marked difference in eIF6 expression between the tumor and non-tumor groups, and the difference was statistically significant." (PMID 34922580, 2021). "Moreover, knockout of eIF6 in mice avoided MYC-induced lymphomagenesis and prolonged tumor-free survival tumor growth." (PMID 34016142, 2021). "Here we performed in silico analyses, evaluated the protein levels of EIF2S1, EIF5A and EIF6 in tumour samples and non-neoplastic tissue controls obtained from 145 patients, and correlated these results with clinical outcome data, including tumour site, stage, adjuvant radiotherapy and survival." (PMID 34830804, 2021). "The current study revealed that eIF6-related signaling pathways activated in HCC were enriched in ribosome biogenesis, cell cycle and mTOR-related cancer signaling pathway, which may stimulate tumor proliferation and invasion." (PMID 34016142, 2021). "Thus, besides the tumor marker CEA and CA 19–9, eIF6 and IMP2 may be used as a prognostic biomarker for overall survival in GBC patients and might be used as a potential therapeutic approach in future." (PMID 32867709, 2020). "Indeed, a study has emphasized that the total depletion of eIF6 could delay tumorigenesis and reduced tumor growth without negative side effects on normal growth in mice, which suggested that eIF6 might be an impactful therapeutic target for cancer treatment." (PMID 34016142, 2021). "EIF6 and TES both are involved with the cytoskeleton, EIF6 helps link ITGBB4 to the cytoskeleton, and TES is a scaffold protein that has roles in cell adhesion, cell spreading, reorganization of the actin cytoskeleton, regulates cell proliferation, and may act as a tumor suppressor." (PMID 26892349, 2016).
cancer (34 papers, 2012 to 2024). A tumor composed of atypical neoplastic, often pleomorphic cells that invade other tissues. "eIF6-Y151A mutation also markedly sensitized cancer cells and inhibited cell proliferation in response to nutrient stress induced by serum starvation." (PMID 36651285, 2023). "Cancer cells also overexpress eIF6, an anti-association factor that binds to 60S ribosome at the 40-60S interface and interfere with 40-60S ribosome subunit joining." (PMID 36187485, 2022). "Due to its roles in ribosome biogenesis and in the regulation of translation, eIF6 is over-expressed in multiple types of cancer, and its over-expression is often associated with increased tumor aggressiveness." (PMID 33245766, 2020). "Our data are in agreement with the observation that mutation of eIF6 Ser235 to Ala greatly reduces cancer growth in vivo, more efficiently than in vitro." (PMID 26462016, 2015). "EIF6 plays a key role in the biosynthesis and function of ribosomes, and dysregulation of eIF6 is closely associated with the formation and development of cancers." (PMID 38671354, 2024). "This marked effect of both the N106S and Y151A mutations of eIF6 in inhibiting growth of cancer cells further highlights the significance of targeting the eIF6–60S interaction interface as an effective strategy for cancer therapeutics." (PMID 36651285, 2023). "There are 4 genes (UACA, PTTG1IP, PIGR, CD81) of this GO term may interacted with ACTR2, EIF6 and hsa-miR-139-5p at the same time, and they play an important role in cancer associated pathway: apoptotic process (UACA, PTTG1IP) and immunity (PIGR, CD81)." (PMID 37365497, 2023). "In addition to cancer cells, eIF6 antiassociation activity is pivotal in the phenotype caused by loss of function mutations of SBDS and eFl1." (PMID 31936702, 2020). "Therefore, the anti-cancer role of eIF6 inhibition may be linked to its metabolic effect, counteracting Myc action." (PMID 26383020, 2015). "Disrupting eIF6 activity has thus been proposed to be a therapeutic strategy for the treatment of certain cancers and SDS." (PMID 36651285, 2023). "Based on these analyses, we selectively targeted the Y151 and N106 residues and show for the first time that perturbing a residue in the eIF6–60S interface markedly affects cancer cell proliferation through disruption of binding to uL14." (PMID 36651285, 2023). "eIF6 is overexpressed in several cancers including colon, ovarian and breast cancers and enhanced expression is correlated with a poor prognosis." (PMID 36651285, 2023). "Establishing these key interfaces thus provide a therapeutic framework for targeting eIF6 in cancers and SDS." (PMID 36651285, 2023). "This will enable the development of novel therapeutics that target eIF6 for the treatment of cancers and SDS." (PMID 36651285, 2023). "Disrupting key residues in the eIF6–60S binding interface markedly limits proliferation of cancer cells, which highlights the significance of therapeutically targeting this interface." (PMID 36651285, 2023). "This study also provides insights into the potential role of eIF6 in pan-cancer epigenetic regulation." (PMID 35707354, 2022). "In this respect, translation initiator eIF6 has been proved as a pro-tumor factor in several cancers." (PMID 35707354, 2022). "It is curious that clofazimine has been proposed as an anti-cancer agent acting that interferes with the Wnt pathway given the well-known capability of eIF6 to enforce Wnt signaling." (PMID 35887068, 2022). "The patients with low-eIF6 expression survived longer than that of eIF6 over-expression in seven types of cancers." (PMID 35707354, 2022). "Overexpression of eIF6 increased cancer cell motility and invasion in CRC, in turn silencing of eIF6 significantly reduced the proliferation rate and the clonogenicity in HCT-116 CRC cell lines." (PMID 36387239, 2022).
cancer (continued). "Among the different types of cancer, high-eIF6 expressed patients had significantly lower survival rates than low-eIF6 expressed patients in SKCM, LGG, LIHC, LUAD, and PAAD." (PMID 35707354, 2022). "A recent study by LJ found that eIF6 activated a variety of AKT-related cancer signaling pathways, such as p-AKT\MMP1\cyclinD1\Bcl2." (PMID 36387239, 2022). "Among them, about 50% of the cancers’ survival rates were lower in the eIF6 higher expression group." (PMID 35707354, 2022). "Although overexpression and oncogenic functions of eIF6 have been documented in other cancers, the role and biological functions of eIF6 in ESCA remains poorly understood." (PMID 35794622, 2022). "Correspondingly, pan-cancer clustering analysis indicated the expression level of intermediate filament proteins was correlated with that of eIF6 expression." (PMID 35707354, 2022). "More higher-methylated genes were observed in the low-eIF6 group than that high-eIF6 group in all five types of cancers, suggesting eIF6 is an effective de-methylation regulator." (PMID 35707354, 2022). "We investigated the survival rate of 33 common types of cancers and found that the up-regulation of eIF6 was generally accompanied lower-survival rate." (PMID 35707354, 2022). "Depletion of eIF6 (using specific siRNA-mediated knockdown) in Mz-ChA-2 and TFK-1 cell lines inhibit cell proliferation and induced apoptosis, while EIF6 over-expression increases the motility and invasiveness of cancer cells." (PMID 33413124, 2021). "Our study explained the underlying mechanism of eIF6-related phenotypes and emphasized the critical part of the AKT signaling pathway in eIF6-mediated cancer." (PMID 34922580, 2021). "eIF6 is also believed to be a cancer-related biomarker and a potential therapeutic target for malignant tumors." (PMID 34922580, 2021). "The diagnostic power of eIF6 was verified by receiver operating characteristic curve (ROC) analysis and its prognostic value was assessed by KaplanMeier analysis, and then related biological functions of eIF6 were determined in vitro and in vivo cancer models." (PMID 34016142, 2021). "Nucleolar ribosome processing factors, such as eukaryotic translation initiation factor 6 (eIF6), pygopus (Pygo) and thyroid cancer 1 (TC1), participate in the ribosome biogenesis process and regulate Wnt signalling at different levels." (PMID 32896929, 2020). "The patient with AML and a complex karyotype, UPN 92, exhibited increased levels of EIF6; it is worth noting that numerous studies have demonstrated highly aberrant overexpression of EIF6 in human cancer." (PMID 31908654, 2020). "In short, a partial targeting of the antiassociation activity of eIF6 is beneficial for at least two pathological contexts: Schwachman–Diamond syndrome and cancer cells." (PMID 31936702, 2020). "EIF6 is potential biomarker for cancer as it downstream modulator of cell division resulting in oncogenesis." (PMID 32139710, 2020). "The phosphorylation of Ser235 residue on eIF6 is necessary for transformation and cancer development." (PMID 26462016, 2015). "One of the translation factors recently demonstrated to have a role in the control of protein synthesis and aberrantly expressed during cancer is the eukaryotic initiation factor 6 (eIF6)." (PMID 25886394, 2015). "In conclusion, our results contribute to shed light on the role of eIF6 in the onset and progression of cell transformation, thus suggesting a molecular platform for developing new anti-cancer strategies." (PMID 25886394, 2015). "Second, we have shown that eIF6 activity in cancer is necessary for dissociating inactive 80S subunits." (PMID 26462016, 2015). "Taken together our data indicate that eIF6 activity in cancer cells is necessary for keeping ribosomes dissociated, and for initiating new protein synthesis." (PMID 26462016, 2015). "The switch to glycolysis and fatty acid synthesis induced by eIF6 in a cell autonomous fashion has implications in cancer." (PMID 26383020, 2015).
cancer (continued). "Multiple studies have reported involvement of eIF6 in tumorigenesis and cancer progression." (PMID 39409166, 2024). "This marked effect of Y151A mutation in inhibiting growth of cancer cells provides the first genetic proof of concept that targeting the eIF6–60S interaction interface could be an effective strategy for cancer therapeutics." (PMID 36651285, 2023). "Thus, a dosage threshold of inhibiting eIF6 should also be taken into consideration for therapeutic screening of compounds to target eIF6–60S interactions in SBDS mutant cells versus cancers and to minimize side effects." (PMID 36651285, 2023). "Furthermore, pan-cancer analysis revealed that the up-regulation of eIF6 is associated with demethylation and higher expression levels of intermediate filament keratins, which may account for the increased proliferation and migration rates in multiple types of cancer cells." (PMID 35707354, 2022). "eIF6 is rate limiting for the growth of several cancer cells with active RAS or Myc amplification." (PMID 35887068, 2022). "GEPIA analysis revealed a landscape of thirty-three different types of cancers influenced by eIF6." (PMID 35707354, 2022). "The eIF6 mRNA expression was analyzed in pan cancers in the TCGA database." (PMID 35794622, 2022). "In cancer, nutrient signaling pathways strongly converge on two initiation factors, eIF4E and eIF6." (PMID 35887068, 2022). "Cancer stroma exhibited significant differences in overexpression also for the subunits eIF6." (PMID 35718769, 2022). "The exact role of eIF6 in cancer cells remains to be determined." (PMID 36187485, 2022). "We first compared the survival rate of 33 common types of cancers during the up-regulation of eIF6." (PMID 35707354, 2022). "The transformation of eIF6 from cytoplasm to nucleus may indicate a new perspective for the treatment of this type of cancer." (PMID 34922580, 2021). "However, eIF6 is also located in individual cells’ nucleolus, like HeLa, A431, Colon adenoma, and cancer cell lines." (PMID 34922580, 2021). "Given the powerful translation control capabilities of eIF6, we began to explore whether it continues to be important in cancer development." (PMID 34922580, 2021). "According to previous studies, eIF6 is abnormally expressed in human cancer tissues." (PMID 34922580, 2021). "This indicated that accelerating the nuclear transport of eIF6 may be closely related to the invasion and metastasis of cancer." (PMID 34922580, 2021). "Moreover, it is confirmed that eIF6 can positively regulate AKT-related cancer signaling and contribute to the malignant behavior of CRC." (PMID 34016142, 2021). "Knockdown of eIF6 can significantly inhibit this cancer-promoting effect." (PMID 34922580, 2021). "Therefore, in this part of study, we concluded that eIF6 activated mTOR-related multiple cancer signaling pathways to promote the malignant progression of human HCC." (PMID 34016142, 2021). "A high expression of eIF6 correlates with human cancer malignancy and progression." (PMID 31936702, 2020). "Studies in mice have unequivocally shown that eIF6 levels control cancer progression and mortality." (PMID 31936702, 2020). "Next, we analysed in an ex-vivo experiment the requirement for eIF6 on 80S cancer ribosomes." (PMID 26462016, 2015). "There is substantial body of evidence that eIF6 is rate-limiting for cancer cells." (PMID 26462016, 2015). "Full understanding of the role eIF6 plays in the metastatic process is important, also in view of the fact that this factor is a potentially druggable target to be exploited for new anti-cancer therapies." (PMID 25886394, 2015). "Our findings also indicate that the mechanism of action by which RPL24 deficiency reduces expression of these proteins essential for cancer cell viability involves failure of 40S and 60S ribosomal subunit joining into functional 80S ribosomes by retention of eIF6 on 60S subunits." (PMID 24970821, 2014).
cancer (continued). "This threshold effect could also explain the paradox of the strategy to target the eIF6–60S interaction interface in cancers to inhibit growth whereas targeting the same interface in SDS patients can be used to rescue the slow growth phenotype and cellular fitness." (PMID 36651285, 2023). "Targeting eIF6 could notably suppress cancer cell proliferation and induce cancer cell apoptosis." (PMID 36435920, 2023). "However, because eIF6 is a rate-limiting translation regulator, we hypothesized that elevated eIF6 levels aided cancer progression and thus resulted in a worse prognosis by limitation the protein synthesis." (PMID 35707354, 2022). "Furthermore, an increasing number of studies have demonstrated that there is a highly aberrant expression of eIF6 in various types of human cancer including colorectal cancer, head and neck carcinoma, malignant mesothelioma, acute promyelocytic leukemia and NSCLC." (PMID 33148274, 2020). "Therefore, our findings may at least partially explain the anti-cancer role of eIF6 inhibition in vivo." (PMID 26462016, 2015). "As a transcription factor, CEBPB was reported to be translationally regulated by EIF6 and regulate the MAPK pathway in cancer." (PMID 35459206, 2022). "Our studies elucidated the crucial role of eIF6 in the progression of HCC and provided a potentially valuable biomarker for the diagnosis and prognosis of this cancer." (PMID 34016142, 2021). "To further confirm eIF6 as a novel promising target for HCC, we performed knockdown experiments to investigate the biological function of eIF6 in vivo and in vitro cancer model." (PMID 34016142, 2021). "Therefore, modulation of eIF6 activity or expression may exert an innovative treatment for cancers." (PMID 33148274, 2020). "Recent studies also showed that eIF6 could regulate CASP3-related apoptosis signaling in NSCLC and activate multiple AKT-related cancer signaling pathways in CRC." (PMID 34016142, 2021). "Specific reports for HNSCC may not be available for all the genes of interest but published studies clearly document the cancer involvement for MMP24, EIF6 FAM83C and GDF5." (PMID 29371888, 2018).
genetic disorders (2 papers, 2023 to 2025). "A number of potential OA GWAS effector genes have been identified, including some that have been implicated in Mendelian diseases with joint and skeletal abnormalities, such as BICRA (also known as GLTSCR1), EIF6, CHST3, and FBN2." (PMID 37579195, 2023).
infection (2 papers, 2015 to 2025). The state of being infected such as from the introduction of a foreign agent such as serum, vaccine, antigenic substance or organism. "To investigate if eIF6 acutely controlled ATP levels, we either silenced eIF6 by lentiviral-mediated shRNA in wt hepatocytes or re-expressed eIF6 by lentiviral-mediated infection in het hepatocytes." (PMID 26383020, 2015).
hematological disorders (1 paper, 2022). "Focusing on the SDS predisposition to hematological malignancies, a growing interest in eIF6 and its role in ribosome maturation prompted two different types of studies." (PMID 36035165, 2022).